CTCF (CCCTC-binding factor)
Description:
Chromatin binding factor that binds to DNA sequence specific sites and regulates the 3D structure of chromatin. Binds together strands of DNA, thus forming chromatin loops, and anchors DNA to cellular structures, such as the nuclear lamina. Defines the boundaries between active and heterochromatic DNA via binding to chromatin insulators, thereby preventing interaction between promoter and nearby enhancers and silencers. Participates in the allele-specific gene expression at the imprinted IGF2/H19 gene locus. On the maternal allele, binding within the H19 imprinting control region (ICR) mediates maternally inherited higher-order chromatin conformation to restrict enhancer access to IGF2 (By similarity). Mediates interchromosomal association between IGF2/H19 and WSB1/NF1 and may direct distant DNA segments to a common transcription factory (By similarity). Regulates asynchronous replication of IGF2/H19 (By similarity). Plays a critical role in gene silencing over considerable distances in the genome (By similarity). Preferentially interacts with unmethylated DNA, preventing spreading of CpG methylation and maintaining methylation-free zones. Inversely, binding to target sites is prevented by CpG methylation. Plays an important role in chromatin remodeling. Can dimerize when it is bound to different DNA sequences, mediating long-range chromatin looping. Causes local loss of histone acetylation and gain of histone methylation in the beta-globin locus, without affecting transcription. When bound to chromatin, it provides an anchor point for nucleosomes positioning. Seems to be essential for homologous X-chromosome pairing (By similarity). May participate with Tsix in establishing a regulatable epigenetic switch for X chromosome inactivation. May play a role in preventing the propagation of stable methylation at the escape genes from X-inactivation. Involved in sister chromatid cohesion. Associates with both centromeres and chromosomal arms during metaphase and required for cohesin localization to CTCF sites. Plays a role in the recruitment of CENPE to the pericentromeric/centromeric regions of the chromosome during mitosis. Acts as a transcriptional repressor binding to promoters of vertebrate MYC gene and BAG1 gene. Also binds to the PLK and PIM1 promoters. Acts as a transcriptional activator of APP. Regulates APOA1/C3/A4/A5 gene cluster and controls MHC class II gene expression. Plays an essential role in oocyte and preimplantation embryo development by activating or repressing transcription (By similarity). Seems to act as tumor suppressor.
Synonyms: FAP108; CFAP108; MRD21
Tractability: Small molecule: a structure with a bound ligand is known. PROTAC: UniProt records ubiquitination sites on it; ubiquitination databases record sites on it; its protein half-life has been measured.
Gene: Protein-coding gene on chromosome 16 (67,561,831 to 67,639,189, forward strand). Ensembl gene ENSG00000102974.
Subcellular location: Nucleus, nucleoplasm; Chromosome; Chromosome, centromere
Subcellular location (Human Protein Atlas): Nucleoplasm
Pathways (Reactome):
Chromatin organization: CHD6, CHD7, CHD8, CHD9 subfamily
Developmental Biology: Activation of anterior HOX genes in hindbrain development during early embryogenesis
Gene Ontology:
Molecular function: chromatin insulator sequence binding; DNA-binding transcription factor activity; DNA-binding transcription repressor activity, RNA polymerase II-specific; protein binding; RNA polymerase II cis-regulatory region sequence-specific DNA binding; sequence-specific DNA binding; transcription cis-regulatory region binding; transcription coregulator binding; zinc ion binding; chromatin binding; chromatin loop anchoring activity; cis-regulatory region sequence-specific DNA binding; DNA binding; sequence-specific double-stranded DNA binding
Biological process: chromatin looping; epigenetic regulation of gene expression; genomic imprinting; negative regulation of cell population proliferation; negative regulation of DNA-templated transcription; negative regulation of transcription by RNA polymerase II; positive regulation of DNA-templated transcription; positive regulation of gene expression; positive regulation of transcription by RNA polymerase II; protein localization to chromosome, centromeric region; regulation of centromeric sister chromatid cohesion; regulation of transcription by RNA polymerase II; negative regulation of gene expression; regulation of DNA-templated transcription
Cellular component: chromosome; chromosome, centromeric region; condensed chromosome; nucleolus; nucleoplasm; nucleus
Genetic constraint (gnomAD): Loss-of-function variants: 7 observed, 64.25 expected, observed/expected ratio (o/e) 0.11, 90% interval 0.061 to 0.2. The upper end of that interval is the gene's LOEUF score, 0.2, which puts it in group 1 of 6, group 1 being the genes least tolerant of losing a copy. Missense variants: 510 observed, 910.42 expected, observed/expected ratio (o/e) 0.56, 90% interval 0.52 to 0.6. Synonymous variants: 360 observed, 310.72 expected, observed/expected ratio (o/e) 1.16, 90% interval 1.06 to 1.26.
Gene-disease validity (ClinGen):
ClinGen rates the evidence that CTCF causes each of these diseases.
syndromic intellectual disability (autosomal dominant): Definitive. A intellectual disability that is part of a larger syndrome.
Cancer hallmarks: genome instability and mutations (suppresses)
Homologues: Orthologues: chimpanzee CTCF (100% identical), macaque CTCF (99% identical), rabbit CTCF (99% identical), dog CTCF (99% identical), pig CTCF (99% identical), mouse Ctcf (99% identical), rat Ctcf (99% identical), guinea pig CTCF (96% identical), tropical clawed frog ctcf (87% identical), zebrafish ctcf (78% identical). Paralogues in human: CTCFL (41% identical), ZNF84 (19% identical), ZNF91 (19% identical), ZBTB48 (18% identical), ZNF184 (18% identical), ZNF420 (18% identical), ZNF574 (18% identical), ZNF160 (18% identical), ZNF107 (17% identical), ZNF729 (17% identical), ZNF99 (17% identical), ZNF594 (17% identical), and 24 more.
Diseases named in the same sentence as CTCF in open-access papers:
CTCF is named in the same sentence as 218 diseases in open-access papers, as found by Europe PMC text mining. Sharing a sentence is not in itself a finding about the gene and the disease. The quoted sentences say what the papers report.
breast carcinoma (108 papers, 2004 to 2025). "Prostate, ovarian and breast cancers frequently feature hemizygous deletions of CTCF and loss of one allele of CTCF in kidney and endometrial cancers correlates with poor patient survival." (PMID 35993175, 2022). "Another important regulator of the ER transcriptional program is the DNA-binding protein CTCF, which is also found to be mutated in luminal breast cancers." (PMID 35774123, 2022). "Similar to what we observed in breast cancer models, the loss of one copy of CTCF increased the capacity of MCF10A to invade through a Matrigel matrix." (PMID 36037342, 2022). "Mutations in the CTCF gene have been reported in breast cancer, endometrial cancer, and ovarian cancer." (PMID 35011637, 2021). "In normal tissues and breast cancer cells, PARylated CTCF predominates upon cell cycle arrest but transitions to a hypo-PARylated form in proliferating cells, which is also associated with breast cancer progression." (PMID 33411704, 2021). "This study indicates that loss of Nm23-H1 in aggressive breast cancer is apparently caused by downregulation of CTCF and EGR1, which potentially drive Nm23-H1 expression to promote a less invasive phenotype." (PMID 33436746, 2021). "Here, we demonstrate that prostate and breast cancers within The Cancer Genome Atlas (TCGA) exhibit frequent copy number loss of CTCF and that this loss is associated with increased DNA methylation events that occur preferentially at CTCF binding sites." (PMID 32503656, 2020). "In breast cancers, a similar preference for CTCF CN loss tumors to preferentially direct hypermethylation events to CTCF binding sites was seen." (PMID 32503656, 2020). "For example, it has been shown that CTCF knockdown causes an anti‐apoptotic effect in breast cancer cells." (PMID 31736271, 2020). "In DNA modification genes we found, several studies showed that CN loss of CTCF at 16q22.1 and its low expression occurred in breast cancer and Wilms tumor of the kidney 20,21." (PMID 31892969, 2020). "Studies have indicated that the mutation in CTCF is associated with the onset of breast cancer, prostate cancer, and Wilms' tumors, suggesting that this subtype mainly contains the tumors in early stages." (PMID 33324444, 2020). "The intersection of CTCF binding sites obtained in our experiments with CTCF sites identified in breast cancer cells MCF7 by the ENCODE consortium, reveals the overlap of 67% and 19.6% of CTCF sites in control and treated cells, respectively." (PMID 29981477, 2018). "Uterine carcinosarcomas and gastric cancers display a mutation rate of CTCF of approximately 5% followed by colorectal, bladder, and breast cancers which display mutation rates of CTCF in 4.87%, 3.22%, and 2.21% of cases examined, respectively." (PMID 30275357, 2018). "The METABRIC breast cancer study identified 44 different CTCF mutations (2.1% of samples) of which 20 mutations (45.5%) are considered likely oncogenic." (PMID 30275357, 2018). "CDC6, which is found in the COSMIC Gene Census database, is top-ranked for all TFBS’s and also for the CTCF double-hit mutations, with two mutations in breast cancer." (PMID 29354286, 2018). "In this subset of endometrioid and breast cancers, CTCF mutations were identified in 40% of samples including inactivation of specific zinc fingers (ZFs) of CTCF that would lead to altered DNA binding." (PMID 30513694, 2018). "We next investigated the underlying mechanism involved in CTCF-mediated inhibition of migration and invasion in breast cancer cells." (PMID 29212169, 2017). "Although CTCF deletion or mutation has been associated with human breast cancer, the role of CTCF in breast cancer is questionable." (PMID 29212169, 2017). "Recently, several cancer genome projects showed that CTCF mutations are significantly associated with breast cancer, head and neck cancer, and uterine cancer." (PMID 27632082, 2016).
breast carcinoma (continued). "Data from several recent cancer genome projects showed that CTCF mutations are significantly associated with breast cancer, head and neck cancer, and uterine cancer." (PMID 27632082, 2016). "In a panel of breast cancer cell lines, heightened CTCF expression was associated with apoptosis resistance." (PMID 26443201, 2015). "CTCF levels are elevated in breast cancer cell lines and tumors and are associated with resistance to apoptosis." (PMID 24393203, 2014). "In breast cancer cells, the loss of CTCF is associated with CpG island methylation and the gain of repressive histone modifications such as histone H3 K9 trimethylation and histone H3 K27 trimethylation." (PMID 23056006, 2012). "The CTCF gene has been mapped to the chromosome band 16q22.1 that shows frequent loss of heterozygosity in breast cancer." (PMID 15354217, 2004). "CCCTC-binding factor (CTCF) is a central regulator of higher-order chromatin structure that undergoes copy number loss in over half of all breast cancers, but the impact of this defect on epigenetic programming and chromatin architecture remains unclear." (PMID 36037342, 2022). "In this study, we demonstrated that a global loss of insulation of subTAD domains, caused by reduced pools of CTCF, may promote breast cancer progression." (PMID 36037342, 2022). "As such, we speculate that CTCF mutations are a metastatic driver in up to 2% of metastatic breast cancers." (PMID 32374727, 2020). "The increase in CTCF was also linked to the resistance of breast cancer cells to apoptosis." (PMID 33204322, 2020). "CTCF is reported to be associated with resistance to apoptosis in breast cancer." (PMID 29485617, 2018). "We investigated the biological functions of CTCF in breast cancer and the underlying mechanism." (PMID 29212169, 2017). "Furthermore, increased levels of CTCF have been associated with resistance to apoptosis in breast cancer and ALL." (PMID 28977939, 2017). "In breast cancer cells, both CTCF mutations and altered expression of CTCF are reported." (PMID 25340699, 2014). "However, the precise role of CTCF in breast cancer and the underlying molecular mechanism remain largely unknown." (PMID 29212169, 2017). "Later carcinogenic insults or exposure to breast cancer-associated fibroblasts might augment hypermethylation at region D and thus impaired its binding to transcription-prone histone markings, cofactors, as well as to CTCF." (PMID 22615834, 2012). "Our study together with these reports supported the model of MEG3/CTCF-CXCR4 axis in the cell migration of breast cancer development, in which CTCF serves as a transcription activator." (PMID 40548301, 2025). "In contrast, since the expression of MEG3 is lost or significantly reduced in breast cancer cells, CTCF is recruited to the promoter/enhancer region of CXCR4 to promote the transcription." (PMID 40548301, 2025). "The interaction between TFIIIC and CTCF seems to be context-dependent as it is observed in serum-starved breast cancer cells but disappears upon serum stimulation." (PMID 40762516, 2025). "In this study, we observed hypoxia-induced upregulation of PRMT5 via the CTCF in human breast cancer cells." (PMID 41150697, 2025). "To further investigate, we identified a dataset from GEO (GSE78113) that includes ChIP-sequencing results for multiple enhancer markers (H3K27ac, H3K4me1, H3K4me3, and CTCF) in the Breast Cancer Cell Line-MCF-7, both under normal and hypoxic conditions." (PMID 39734414, 2024). "Here we probe if the transcription factor CTCF plays a role in the differential expression of ESR1 in the breast cancer cell lines MCF-7 (ESR1+) and MDA-MB-231 (ESR1-)." (PMID 38236307, 2024). "In human breast cancer cells, CTCF can inhibit the expression of the pro-apoptotic protein Bax, thereby exerting an anti-apoptotic effect." (PMID 39623397, 2024). "Genetic alterations in CTCF have been observed in numerous cancers, including colorectal cancer and breast cancer." (PMID 39506204, 2024).
breast carcinoma (continued). "It has been reported that the overexpression of CTCF impedes the proliferation and metastasis of breast cancer cells by deactivating the nuclear factor-kappaB pathway in breast cancer cells." (PMID 38565950, 2024). "CTCF, a transcription factor containing 11 zinc fingers (ZFs), has been reported to have involvement in various cancers including breast cancer, hepatocellular carcinoma, lung cancer and prostate cancer." (PMID 38436544, 2024). "For instance, CTCF binds to exon 1 of the hTERT gene and inhibits its expression in breast cancer cells." (PMID 37612721, 2023). "We also observed coincident binding throughout the TAD of transcription factors relevant to breast cancer, including CTCF, FOXA1, ESRRA (a relative of the estrogen receptor ER), and MYC." (PMID 37541849, 2023). "For example, the chromosomal loops on chr11 are complemented by the binding of CTCF, FOXA1, and ESRRA, molecules with potential roles in breast cancer risk." (PMID 37541849, 2023). "To demonstrate the in situ efficiency of BIND&MODIFY, we explored the H3K27me3/CTCF status in the breast cancer cell lines MCF-7 and 4T1 using BIND&MODIFY and cross-validated it with ChIP-seq." (PMID 36991510, 2023). "We also found that CTCF expression was correlated with NQO1-AS in the TCGA breast cancer dataset (ρ = 0.4, P = 1 × 10−16)." (PMID 37169843, 2023). "To determine if increasing the CTCF expression elicits similar changes in a breast cancer cell line, we generated MDA-MB-231 cells overexpressing either GFP or CTCF." (PMID 35008373, 2022). "Next, we validated the impact of CTCF levels on invasiveness by comparing the effects of short hairpin RNAs (shRNAs) against CTCF (shCTCFs) or scrambled shRNA (shCTL) in MCF7 cells, a widely used, CTCF wild-type (WT) breast cancer cell line." (PMID 36037342, 2022). "To elucidate the 3D chromatin organization of breast cancer cells, we performed in situ Hi-C12 and CTCF ChIP-seq (chromatin immunoprecipitation sequencing) in HMECs and five breast cancer cell lines." (PMID 35513575, 2022). "Altogether, these studies confirm a relationship between low CTCF expression and increased invasiveness in distinct breast cancer models." (PMID 36037342, 2022). "Overexpression of CTCF was reported to initiate multiple cancer types including breast cancer, hepatocellular carcinoma, lung cancer, prostate cancer, and colorectal cancer." (PMID 35378133, 2022). "Using svMIL2, we were able to identify pathogenic non-coding SVs that alter expression of known cancer genes by disrupting CTCF loops in breast cancer." (PMID 34257393, 2021). "Other work has revealed that in breast cancer cells, cell cycle genes are regulated by estrogen receptor-mediated interactions with CTCF localized to the nuclear lamina." (PMID 33411704, 2021). "Out of 94 predicted driver genes affected by SVs through CTCF loop disruption in breast cancer, two are reported as cancer-driving by the CGC." (PMID 34257393, 2021). "Decreases in CTCF expression alter the DNA methylation landscape in prostate and breast cancer, two of the most common human tumors." (PMID 32503656, 2020). "As miR-375 is a key driver of cell proliferation, these findings confirm the tumor suppressor role of CTCF in breast cancer." (PMID 33194751, 2020). "We apply GVITamIN on a breast cancer cohort and identify well-known cancer-related transcription factors, such as CTCF, LEF1, and FOXA1, as TFs dysregulated by breast cancer-associated SNPs." (PMID 32850701, 2020). "Surprisingly for a tumor suppressor, CTCF levels were increased in breast cancer compared with normal breast tissues." (PMID 33204322, 2020).